IFNB1 (interferon beta 1)
Diseases named in the same sentence as IFNB1 in open-access papers (continued):
Sharing a sentence is not in itself a finding about the gene and the disease.
tumor (continued). "In line with this, we found in the TCGA dataset that loss of expression of IFNA13, IFNA21, IFNA6, IFNA8, IFNB1, or IFNW1 was correlated to poor survival, increasing the evidence for the importance of the tumor-stroma microenvironment interaction in gliomagenesis." (PMID 27172220, 2016). "The strong pro-tumor phenotype of Ifnb1−/− mice confirms the hypothesis that the expression of all alpha IFNs strongly depends on the previous IFN-β expression." (PMID 28066438, 2016). "It has been reported that IFNB1 could either suppress or promote tumor growth." (PMID 40282455, 2025). "Pro-angiogenic TANs from Ifnb1−/− mice were shown to have a prolonged life span in tumor-bearing mice, which could be explained by lower expression of FAS, active caspase 3 and 9, and an imbalance in the expression profiles of pro-apoptotic and anti-apoptotic genes." (PMID 36555469, 2022). "Mechanistically, Rag GTPase activity controls IRF expression to prime IFN transcription, while upon PRR stimulation, the tumor suppressor FLCN recruits p38 MAPK to lysosomes, where Rag-dependent p38 phosphorylation stabilizes Ifnb1 mRNA." (PMID 41571995, 2026). "Interestingly, in vitro, irradiation of 4T1 carcinoma cells in the absence of the tumor stroma showed upregulation of ISGs, except Ifnb1, suggesting that the cGAS‐STING pathway may be variant in 4T1 cells and that tumor stromal cells play a critical role in RT‐activated immune responses." (PMID 40470716, 2025). "To identify the cellular source of Ifnb1 expression in the TME, we used RNAscope on Prf1–/–MMTV-PyMT tumor sections." (PMID 40627458, 2025). "To evaluate the contribution of IFNB1 and GM-CSF expression by MOC2SIIN to overall tumor control in vivo, we combined two cell populations: IFNB1-expressing MOC2SIIN cells (MOC2SIIN-IFNB1) and GM-CSF-expressing MOC2SIIN cells (MOC2SIIN-GM-CSF)." (PMID 40282455, 2025). "We inoculated the heterogeneous cell mixtures from the IFNB1/GM-CSF group (total of 5 × 106 cells per mouse) into both immunodeficient NSG mice and immunocompetent C57BL/6 mice and compared tumor growth." (PMID 40282455, 2025). "Of them, IFNB1 and IFNG, both belonging to the interferon family, play crucial roles in anti-tumor immunity." (PMID 40928500, 2025). "It is well established that type I interferons, IFNB1 and IFNA1, play a crucial role in the anti‐tumor immune response." (PMID 38627900, 2024). "The three genes (CALR, IFNB1, and IFNG) were involved in anti-tumor immunity, which improved the predictive performance of this signature." (PMID 38023241, 2023). "In the presence of MV, we measured a significant induction of IFNB1 expression in all insensitive tumor cells lines and in all healthy cells, even in CEB in which IFNB1 expression was increased 20-fold." (PMID 26539644, 2015). "Our data indicate that IFNB1, together with GM-CSF, may attract DCs to stimulate adaptive immunity, leading to MOC2SIIN tumor regression." (PMID 40282455, 2025). "The observation that tumors regressed in C57BL/6 mice but not in NSG mice confirms that IFNB1 signaling induced adaptive immunity to suppress tumor growth." (PMID 40282455, 2025). "Additionally, IFNB1 and CXCL10 mRNA levels and T-cell infiltration were higher in CT26 tumor tissues treated with I-1." (PMID 40128585, 2025). "(S)-XY-05 dose-dependently increased IFNB1 mRNA levels in CT26 tumor tissues, whereas 100 mg/kg RBN-2397 failed to achieve a similar effect." (PMID 40128585, 2025). "An alternative strategy for IFNB1 delivery into tumor cells is the use of non-viral delivery systems." (PMID 41373826, 2025). "In summary, our data indicate that IFNB1 expression can restore dendritic cell infiltration and function, thereby activating adaptive antitumor immunity in immune-cold MOC2 tumors and leading to effective tumor control." (PMID 40282455, 2025). "In addition, the mRNA expression of IFNB1, CCL5 and CXCL10 was markedly increased in TRIM21-KO tumours after IR treatment." (PMID 36797289, 2023).
tumor (continued). "Multigene expression analysis by qRT–PCR revealed a strong correlation between the expression of human monocytic markers CD14 or CD16 and diverse IFN-I-related genes such as IFNB1, USP18 and IRF7, indicating that human monocytic infiltrates can produce IFN-I within human tumour tissues." (PMID 28248314, 2017). "Even if pDCS are indeed able to express alpha IFNs without previous stimulation, the comparable elevated tumor growth in Ifnb1−/− and Ifnar1−/− mice demonstrates its irrelevance." (PMID 28066438, 2016). "Recent data indicate that spontaneous production of ROS is diminished in the absence of endogenous IFN-β, potentially contributing to the delayed apoptosis of tumor infiltrating neutrophils in Ifnb1−/− mice." (PMID 26648665, 2015). "In contrast, seven out of the fifteen sensitive tumor cell lines expressed IFNB1 in response to the virus (Meso35, 36, 37, 56, 152, 34 and 122), whereas the eight other sensitive tumor cell lines did not." (PMID 26539644, 2015). "On the contrary, tumor cell lines that are unable to develop a type I IFN response are sensitive to MV infection, with the four exceptions, Meso36, 37, 34 and 122, which express IFNA1, IFNB1 and MX1 and are sensitive to MV replication." (PMID 26539644, 2015). "Our findings support the notion that IFNB1 may engage antitumor immunity through DCs to effectively control MOC2 tumor growth without requiring an exogenous antigen expression." (PMID 40282455, 2025). "While Ifnb1 expression on mRNA level was significantly increased in B16 cells irradiated with 3 × 8 Gy, no IFN-β could be detected by ELISA and the cytokine level inside the tumor in vivo was not affected by any treatment." (PMID 33572437, 2021). "As previously reported, Ifnb1 could be induced in vitro by a cGAS-STING agonist, yet in vivo it was more highly expressed in CD45+ cells than in tumor cells; by contrast, other IFNs, particularly Ifne, were not induced by these stimuli in vitro and showed preferential expression in tumor cells." (PMID 36344707, 2022). "In 4 different P7 KP tumor-derived isogenic cell lines with or without Atrx deletion, we found that after transfections with ISD, cells with Atrx deletion had markedly decreased CGAS/STING–mediated Ifnb1 expression." (PMID 37200088, 2023).
cancer (321 papers, 2007 to 2026). A tumor composed of atypical neoplastic, often pleomorphic cells that invade other tissues. "Conversely, in ABCC10-knockout or ABCC10-knockdown cancer cells, the upregulation of pTBK1, pIRF3, and IFNB1 was further amplified in the presence of both exogenous and endogenous cGAMP." (PMID 40770563, 2026). "Conversely, the complement component 5a (C5a)/C5aR1 axis suppresses STING-driven IFNB1 expression in immune responses, suggesting their distinct regulatory effects on cancer cell radiotherapy responses." (PMID 41809048, 2026). "This upregulation of ISGs upon ORMDL3 knockdown was consistent in the MC38 cancer model, where Ifnb1, Ccl5, and Cxcl10 mRNA levels were significantly elevated." (PMID 40126553, 2025). "Among all of the ICD-related genes, CALR showed the highest expression in pan-cancers, while IFNB1 showed the lowest expression." (PMID 36497433, 2022). "Knocking down DUSP11 levels in the recipient cancer cells significantly enhanced the magnitude of IFNB1 transcript induction." (PMID 33184222, 2020). "Similar to the results obtained with the mouse carcinomas, marked upregulation of human Ifnb1 and Mx1 was seen after irradiation with 8 Gy X 1, which was further increased with 8 Gy X 3, while 20 Gy upregulated Trex1." (PMID 28598415, 2017). "In addition, mRNA levels of Tnf and Mx1 (an interferon-stimulated gene linked to Ifnb1 expression) were upregulated in MakA-treated tumors, suggesting a pro-inflammatory TME with enhanced anti-cancer potential." (PMID 41326332, 2025). "Finally, to clarify the source of IFNβ, we collected cancer cells and BM‐MSCs from the DC by sorting, and assessed IFNB1 expression via qPCR." (PMID 38638003, 2024). "Therefore, we applied EV-enriched conditioned media from cocultured cells onto MDA-MB-231 cancer cells and assayed for induction of IFNB1 transcripts." (PMID 33184222, 2020). "Indeed, the TLR3/dsRNA inhibitor complex, a competitive and high affinity inhibitor of dsRNA binding to TLR345, blocked the capacity of J1.1 cell exosomes to induce expression of IFIT1 and IFNB1 in HSC3 cancer cells (J1.1+inh)." (PMID 30389917, 2018). "qRT-PCR results showed that DSF induced IFNB1 expression in a Cu-dependent manner, further confirming the essential role of Cu in DSF-mediated activation of cancer cell-intrinsic innate immunity." (PMID 39990655, 2025). "LY96 emerged as a recurrent biomarker in four cancers (KICH, KIRC, LIHC, and STAD), and IFNB1 was identified in DLBC, KIRP, and STAD." (PMID 41150760, 2025). "To further examine the impact of IFNB1 or GM-CSF on antigen presentation machinery in cancer cells, we analyzed the surface expression of H-2Kb on MOC2 cells expressing either IFNB1 or GM-CSF via viral transduction." (PMID 40282455, 2025). "The levels of cytokines such as IL1a, IFNB1, CD80, CD86, and CXCL10, which are important for inducing an immune response by macrophages within cancer tissue, were upregulated in PBMCs in a RIG-I-dependent manner." (PMID 37543704, 2023). "For example, the MHC class and CD274 work in cancer and immune cells, and CCL5, CXCL10 and IFNB1 are downstream of ISRE and induce immune cell infiltration into cancer tissue." (PMID 37543704, 2023). "Thus, we stimulated each cancer cell line with HT-DNA and measured expression of IFNL1, IFNL2, and IFNB1 after 2, 6, 10 and 20 hours." (PMID 40012911, 2024). "BM‐MSCs, but not cancer cells, had elevated IFNB1 expression after the DC, which was partially reversed by Gap26." (PMID 38638003, 2024). "Transcriptional analyses of IL-6, RSAD2, IFIT1 and IFNB1 following treatment with the CPT analogue topotecan (Top) suggested that 15 and 21 out of 42 human cancer cell lines expressing STING showed increased IL-6 expression >2 fold after 6 and 24 h Top treatment, respectively." (PMID 35087822, 2021).
cancer (continued). "HIV-infected J1.1 cell exosomes and synthetic HIV TAR RNA induced significant expression of TLR3-responsive ISGs IFIT1 and IFNB1 in SCC9 and HSC3 cells, suggesting that TAR RNA-bearing exosomes from HIV-1-infected T cells would signal through TLR3 in cancer cells." (PMID 30389917, 2018). "We also found that exosomes from EBV+ and EBV− cell lines failed to stimulate expression of FOS, c-Myc, and IFNB1, although the exosomes induced significant expression of the ISG IFIT1 in HSC3 cancer cells." (PMID 30389917, 2018).
bacterial infection (59 papers, 2010 to 2025). "Despite its importance during viral or bacterial infections, transcriptional regulation of the interferon-β gene (Ifnb1) in activated macrophages is only partially understood." (PMID 26592194, 2015).
neurological diseases (9 papers, 2017 to 2024). "We also found a negative correlation with a type I interferon-associated responses (IFNB1), often targeted in treatments for neurological diseases to reduce inflammation." (PMID 38907103, 2024).
lung (7 papers, 2016 to 2024). "Upon analysis, expression of the cytokines IFNB1, IFNG (IFN-γ), TNF (TNF-α), TGFB1 (TGF-β), IL1B, IL2, IL6, CXCL8 (IL-8), and IL10 were all significantly increased in ‘mesenchymal’ lung ADC compared to ‘epithelial’ tumors." (PMID 29440769, 2018).
immune diseases (3 papers, 2013 to 2018). "Furthermore, several key genes (e.g., Csf1r, Ifnb1, IL-20, IL-22, IL-24, Jhdm1d, Csf1r, Ifnb1, IL-20, IL-22, IL-24, and Tgfb2 that regulate sex differences in immune diseases) were discovered." (PMID 30246031, 2018).
adenocarcinoma (2 papers, 2020 to 2021). A common cancer characterized by the presence of malignant glandular cells. "A high expression level of HLA-DPA1 was significantly associated with adenocarcinoma histology (p = 0.03), whereas the expression level of IFNB1 was significantly lower in male patients (p = 0.05)." (PMID 34209514, 2021). "Consistent with RIG-I induction, cationic-lipid-mediated transfection of HCV 5′-triphosphate RNA (referred to here as “5′-ppp-RNA”) into the A549 adenocarcinoma human lung epithelial cell line resulted in the induction of both IFNB1 cytokine and ISG15 mRNA transcripts." (PMID 33184222, 2020).
IFNB1 also shares sentences with these, for which no sentence is quoted: relapsing-remitting MS (91 papers); lupus (50); HIV-1 infection (27); Arthritis (23); Obesity (23); pneumonia (21); experimental autoimmune encephalomyelitis (20); Stroke (19); atherosclerosis (14); neuroblastoma (14); Rotavirus infection (14); diabetes (13); lung fibrosis (13); multiple myeloma (13); rheumatoid arthritis (13); dermatomyositis (12); hepatitis C (12); lymphopenia (12); Cognitive impairment (11); malaria (11); osteosarcoma (11); SARS-CoV infection (11); acute myeloid leukemia (10); chronic hepatitis C (10); encephalitis (10); Hepatitis (10); ischemic stroke (10); leukemia (10); liver fibrosis (10); neurodegenerative disease (10).
A further 410 diseases each share a sentence with IFNB1 in 9 papers or fewer.